CD4 (CD4 molecule)
Diseases named in the same sentence as CD4 in open-access papers (continued):
Sharing a sentence is not in itself a finding about the gene and the disease.
viral infection (continued). "Previous research revealed that androgen inhibits murine and human CD4 T cells differentiated into T-helper 1 cells by blocking IL-2 signaling, providing solid evidence for targeting androgen in rescuing immune responses in confronting virus infection." (PMID 36119091, 2022). "HCV may accelerate the depletion of CD4 cells because of the accumulation of dysfunctional immune activation during chronic viral infection." (PMID 36298842, 2022). "Given that polyfunctional T‐cell responses are closely linked to viral control in other viral infections, polyfunctional SARS‐CoV‐2‐reactive CD4 T cells were visualized proportionally as well as analysed quantitatively at 3, 6 and 9 months after recovery from COVID‐19." (PMID 35396852, 2022). "Although CD8+ T cells are consideredimportant for containment of viral infections, loss of CD8+ T cells in an SVV-infected RM acute modelresulted in slightly higher viral loads and prolonged viremia, while CD4 depletionled to higher viral loads, prolonged viremia, and disseminated varicella." (PMID 36865570, 2022). "Recent studies have hypothesized a potential role of Th17 CD4 T lymphocytes (that secrete the IL-17 cytokine upon activation, among others) during viral infection, promoting the secretion of pro-inflammatory cytokines and activating other immune cells." (PMID 36016196, 2022). "Furthermore, one of the receptors for TRAIL, death receptor 5 (DR5), on CD4+T cells plays an important role in T cell regulation through NK cells in the SGs during chronic viral infection." (PMID 36388880, 2022). "Given that the numbers of peripheral B and CD4 T cells were dramatically reduced by coinfections, we next monitored the level of total IgG and serum neutralizing antibody (NAb) in each group of mice at 7 and 10 dpi from the primary virus infection." (PMID 35107382, 2022). "Future research should aim to assess the magnitude and the durability of SARS-CoV-2 vaccine-induced antibody and T cell responses in PLWH with particular focus on those with uncontrolled viral infection and/or who have low CD4+ T cell counts to inform the best strategy for boosting." (PMID 36846557, 2022). "However, patients with simultaneous bacterial and viral infections at admission presented with increased PD-1 expressions on CD4 + and CD8 + T cells, higher PD-L1 expression on CD8 + T cells and CTLA4 expression on CD4 + T cells." (PMID 35246776, 2022). "As we commonly know, the CD4+ T cells are increased after a viral infection." (PMID 35812417, 2022). "Gp120 is critical for virus infection, as the protein is necessary for binding to specific cell surface receptor CD4, mainly expressed on CD4+ T cells, and the coreceptor [e.g., chemokine receptor C-C Motif Chemokine Receptor 5 (CCR5) or C-X-C chemokine receptor type 4 (CXCR4)]." (PMID 36093171, 2022). "In addition to CD8+ T cells, CD4+ T cells are also functionally exhausted during chronic viral infection and their helper functions are compromised." (PMID 35774790, 2022). "While previous studies have demonstrated that most antigen-specific CD4+ T cell clones can give rise to multiple lineages following acute bacterial or viral infection, recent evidence indicates that some clones may also display a biased cell fate decision." (PMID 36255051, 2022). "Eomes has been shown to impact CD4 T cell responses against diverse viral infections." (PMID 36358898, 2022). "Viral infection resulted in the depletion of CD4+ T cells in the gut mucosa and peripheral blood." (PMID 35495669, 2022). "In response to either an acute or persistent viral infection, naïve antigen-specific CD4+ T cells clonally expand and primarily differentiate into either T helper type 1 (Th1) or T follicular helper (Tfh) cells, which support cellular or humoral responses, respectively." (PMID 36255051, 2022). "Thus, CD4+ T cells responding to chronic viral infection are also capable of exhibiting memory-like properties, even in the presence of ongoing viral replication." (PMID 36255051, 2022).
viral infection (continued). "Cytotoxic CD4 T cells are induced during viral infection and vaccination." (PMID 35610643, 2022). "In addition, analyzing the concentration of CD4+ cells in biopsies specimens of patients with NASH, alcoholic or viral disease, a fewer count was found in NASH subjects, confirming the depletion of CD4+ caused by hepatic fat." (PMID 35269846, 2022). "Initial studies reported the in vivo presence of CD4 CTLs in various viral infections." (PMID 35572552, 2022). "Antigen specific CD4+ T cells play a central role in the immune response to a viral infection, as they may reduce disease severity after re-infection by a more rapid clearance of the virus and better overall disease control, as reviewed in." (PMID 35911689, 2022). "Early studies suggested that B cells play an essential role in the clearance of persistent viral infection through antibody production and induction of a competent CD4 T-cell help response in a chronic lymphocytic choriomeningitis virus (LCMV)-infected mouse model." (PMID 36224474, 2022). "TCR transgenic mice specific for a major CD4+ T cell epitope (VP272–86) of TMEV restricted with I-As (018030, SJL.Cg-Tg (TcraTcrbVP2) 1 Bkim/J from the Jackson Laboratory) have been used to investigate the differentiation of CD4+ T cell types during viral infection." (PMID 34067536, 2021). "The immunosuppressive environment characteristic of the liver may dampen the maturation of cytotoxic CD8+ T cells to limit tissue damage, accounting for an important role of CD4 antiviral responses in hepatotropic viral infections." (PMID 33430234, 2021). "Age-associated differences in the responses of CD4+ and CD8+ T cells have been previously reported in response to vaccination against viral (e.g., influenza, yellow fever), bacterial (e.g., Streptococcus pneumonia) and parasitic (e.g., Plasmodium falciparum) infectious diseases." (PMID 33874975, 2021). "Naive CD4+ T cells can differentiate into Th1 and Tfh cells during viral infection." (PMID 34213405, 2021). "This does not mean that earlier studies reporting decreased CD4/CD8 T cell ratios associated to viral infection were inaccurate." (PMID 35054246, 2021). "Viral infection induced-CD4 TRM cells show the enhanced expression of Hobit and Eomes." (PMID 33968018, 2021). "Besides, they are also able to maintain normal rates of peripheral mature CD4+ T cell proliferation to compensate for the cytopathic destruction of CD4+ T cells post-viral infection." (PMID 34544548, 2021). "As CCR4 is preferentially expressed by Th2-polarized CD4 T cells, the recruitment of a less effective Th response against viral infections could support immune evasion." (PMID 34959486, 2021). "In many viral infections, CD4+ effector cells are mainly Th1 subtypes." (PMID 34851958, 2021). "Of note, the BER pathway has been shown to play a pivotal role in repairing DNA damage, especially for 8‐oxoG lesions, as we have recently reported that PGC‐1α and mtTFA are repressed in CD4+ T cells and play a role in compromised mitochondrial functions in the setting of chronic viral infection." (PMID 34752684, 2021). "CD4+ Tscms are efficiently induced after yellow fever vaccination and persist for decades." (PMID 34283810, 2021). "In RMs, natural plasma IL-15 levels during acute SIV were significantly positively correlated with viral infection of CD4+ T cells, and this was attributed specifically to an increase in CD4 on the surface of memory CD4+ T cells between day 7 and 10 in acute SIV." (PMID 34578331, 2021). "It is well known that CD4+ Th17 cells have also been shown to play a role in viral infections." (PMID 33777278, 2021). "In yellow fever vaccination, which confers protection for decades, CD4+ T cells respond faster to the vaccine than CD8+ T cells, and this could be an important aspect in the development of high-quality immune responses and protection." (PMID 33546283, 2021).
viral infection (continued). "We observed that m138 clearly contributes to diminish M25-specific CD4+ T cell proliferation in spleen and lungs of infected mice, but not in salivary glands, where virus specific CD4+ T cells are important for control of the viral infection." (PMID 33459589, 2021). "This population is considered exceedingly cytotoxic and could represent a CD4+ T cell population with cytolytic activity, at least in some viral infections." (PMID 33621210, 2021). "The frequency of CD4+CD25+ Tregs most significantly increased at the early stage of virus infection (about 15 days old) and later stage (about 60 days old), while at about 30 days old, the frequency of CD4+CD25+ Tregs in the immune organs was slightly lower than that of the other days." (PMID 34526112, 2021). "To elucidate whether PDK1 regulates Tfh cell differentiation, we first evaluated the expression of PDK1 in bifurcation of effector CD4+ T cells into Tfh or Th1 cells upon acute viral infection." (PMID 33595435, 2021). "Among CD4+Th cell subsets, naive CD4+T cells differentiated into Tfh cells can promote humoral immunity by mediating the interaction between T cells and B cells, which are essential for the control of viral infections and vaccine responses." (PMID 34603308, 2021). "Together, these data indicate that robust CD4+ T cell responses in the mucosa may play a key role in mitigating acute viral infection." (PMID 34138927, 2021). "However, upon immune challenge, such as viral infections, antitumor responses, and autoimmune disorders, CD4+ CTLs significantly expand in the blood and peripheral tissues." (PMID 34445118, 2021). "Furthermore, CD4+ helper T cells, mainly Th2, have an important role in antibody production by B cells during viral infections or vaccination, triggering the humoral response activation and anti-inflammatory cytokines." (PMID 34834950, 2021). "In addition, CD4+ T cells directly inhibit HIV by promoting other T cells to resist viral infection." (PMID 34603402, 2021). "In addition, a subset of CVIDid patients showed a high percentage of CD4 + T effector memory cells, and CD4 + T effector memory cells re-expressing CD45RA (TEMRA), which are associated with chronic activation such as observed in viral infections." (PMID 34247288, 2021). "CD32 expression might increase on CD4+ T cells as a direct consequence of the virus, either through viral infection and/or antigenic stimulation." (PMID 34220857, 2021). "In the setting of a viral infection, CD4+ T cells differentiate primarily into T helper 1(Th1) effectors, which help cytotoxic CD8+ T cells to lyze infected cells, and into T follicular helper (Tfh) cells, which help B cells to generate highly matured antibodies." (PMID 33430234, 2021). "Furthermore, prophylactic or therapeutic treatment with everolimus or rapamycin prevented HIV-1 acquisition and controlled HIV-1 replication in ongoing viral infection of intestinal CD4+ T cells." (PMID 33637808, 2021). "We observed that a key feature of non-pathogenic SIV-infection of SM is the low level of virus infection of CM T-cells as compared to both CD4 effector memory (EM) T-cells of SM and CM CD4 T-cells of RM." (PMID 34449812, 2021). "Besides, CD4+ T lymphocyte stages can guide clinicians on problematic complications, such as opportunistic and recurrent viral infections, gastrointestinal disease, lymphoma, autoimmunity and inflammation in CVID patients." (PMID 34108596, 2021). "This is in part because HIV-1, as with several other viral infections, is known to increase oxidative stress of CD4+ T cells, and this may be added to the stress of NTP application, especially with increased Vpr expression." (PMID 33647028, 2021). "More recently a study has suggested that SARS-CoV-2 could interact with the CD4 molecule and that CD4-positive cells are permissive to viral infection." (PMID 35965490, 2021).
viral infection (continued). "Thus, our results pinpointed EZH2 as a crucial hub in fostering the CD4 T cell response in the early expansion phase during acute viral infection." (PMID 32999031, 2020). "Taken together, these data validated the hypothesis that EZH2 expression and the subsequent H3K27me3 modification in virus-specific CD4+ T cells were important for early commitment to the TFH cell fate in response to an acute viral infection." (PMID 30842630, 2020). "We found enhanced EZH2 expression in recalled SM CD4 TFH cells and TH1 cells compared to basal EZH2 expression levels in unrecalled ones, suggesting EZH2 might play an important role in regulating CD4 T cell recall responses in acute viral infection." (PMID 32999031, 2020). "Next we determined whether HDAC1/HDAC2 also control CD4+ CTL generation in response to viral infection in vivo." (PMID 32102981, 2020). "The lower number of the CD4+ T cell population in the CD83 KO mice could also have affected the antibody production efficacy after virus infection." (PMID 33302987, 2020). "Additionally, SMARTA TCR Tg mice are useful in comparing distinct anti-viral CD4+ T cell responses between acute and chronic viral infections in humans." (PMID 33353154, 2020). "EZH2 is crucial for CD4 T cell response during acute viral infection." (PMID 32999031, 2020). "However, under a low viral infection, a high level of initial virus-specific CD4+ T cells protects mice from the development of demyelinating disease." (PMID 33086489, 2020). "The EZH2 protein reached peak levels at day 2.5 and then declined to a basal level at day 8, suggesting EZH2 might play a role in regulating virus-specific CD4 T cell responses during the early phase of an acute viral infection." (PMID 32999031, 2020). "EZH2 is indispensable for the metabolic fitness of CD4 T cells in acute viral infection." (PMID 32999031, 2020). "Additionally, mechanisms that control viral infection via anti-viral CD4+ T cells were identified with SMARTA TCR Tg mice." (PMID 33353154, 2020). "Moreover, cytotoxic CD4+ T cells (CD4+ CTLs) can directly induce the apoptosis of target cells that have overexpressed MHC II due to viral infection." (PMID 33297958, 2020). "Interestingly, it has been reported that IL-10 decreases both CM and EM development specifically within the CD4+ T cell compartment in response to viral infection." (PMID 31907034, 2020). "The mRNA levels of Top2α in CD4 T cells isolated from virus-infected patients remained unchanged compared to HS, indicating that Top2α inhibition occurs primarily at the post-transcriptional level during viral infection." (PMID 32193368, 2020). "Therefore, in contrast to transient expression in effector T cells in response to viral infection, Egr2 expression is maintained in PD-1high MP CD4 T cells." (PMID 32709717, 2020). "Moreover, lymphocyte-mediated cytotoxicity by CD4+ T cells has been involved in the control and clearance of viral infections." (PMID 33255617, 2020). "The CD4 T cell response is pivotal for curtailing viral infection." (PMID 32999031, 2020). "Therefore, the initial differentiation of virus-specific CD4+ T cells under the environment of active viral infection appears to play a critically important role in the pathogenesis of TMEV-induced demyelinating disease." (PMID 33086489, 2020). "Our data support a scenario in which activated, virus‐specific CD4 T cells provide help to non‐specific B cells at extrafollicular sites, supporting the production of virus unspecific IgG antibodies during persistent viral infection." (PMID 31724162, 2020). "Therefore, the first cell type accumulated at the site of viral infection appears to be FoxP3+CD4+ T cells." (PMID 33086489, 2020). "CD4+ T cells also play a key role for the establishment of long-term cellular and humoral antigen specific immunity, which is the basis of life-long protection for many viral infections and vaccines." (PMID 33384690, 2020).
viral infection (continued). "In response to viral infections, normally both CD4+ and CD8+ T cells become activated." (PMID 32975374, 2020). "Thus, we identified EZH2 as a novel regulator in virus-specific CD4 T cell expansion during acute viral infection." (PMID 32999031, 2020). "Next, we investigated whether the inhibition of the EZH2-mediated H3K27me3 modification also led to defects in the TFH cell commitment of virus-specific CD4+ T cells in response to a viral infection." (PMID 30842630, 2020). "Indeed, there is strong evidence that miR-155 controls CD8+ and CD4+ T cell activation, proliferation, and cytokine production in vitro and in vivo during viral infection." (PMID 32442188, 2020). "Using this mAb, the subpopulation of CD4 T cell subsets and the variations of these T cell populations were able to explain the helper T cell function for the CD4-positive T cells during viral infection, suggesting the involvement of CD4 T cells in the anti-viral immune response." (PMID 32545330, 2020). "In addition, the initial activation status of virus-reactive CD4+ T cells when encountering viral infection determines the outcome of the disease." (PMID 33086489, 2020). "Since CD4+ and CD8+ T cell responses are essential to eliminating viruses, it is important to understand the underlying mechanisms of anti-viral T cell-mediated immunopathogenesis during viral infections." (PMID 33353154, 2020). "To examine the consequence of increased IFN-λR1 expression on CD4+ T cells, we determined if IFN-λ3 could directly inhibit a viral infection of CD4+ T cells." (PMID 32353085, 2020). "In contrast, FoxP3+CD4+ T cells may be beneficial in controlling prolonged T cell responses in acute viral infections." (PMID 33086489, 2020). "Also, significantly less patients reached the goal of > 10% CD4+CD45RA+-cells in the group with viral infection (HR 0.51, 95% CI 0.30–0.85, p = 0.010)." (PMID 32017805, 2020). "To test this hypothesis, we bred Ezh2fl/fl or Ezh2fl/flCd4-Cre mice with SM mice to probe the role of EZH2 in CD4 T cell responses to acute viral infection." (PMID 32999031, 2020). "To examine the role of NFAT1 and NFAT2 in CD8+ T cell differentiation during acute viral infection, we used mice deficient in NFAT1 (NFAT1−/−, referred as NFAT1 KO) and mice with conditional T cell-specific deficiency of NFAT2 (NFAT2fl/fl CD4-Cre+, referred herein as NFAT2 TKO)." (PMID 30828328, 2019). "However, CD4+ T cells were required for local control of viral infection in the lower female reproductive tract and for protection against lethal intravaginal ZIKV infection." (PMID 30677097, 2019). "However, increasing attention has been paid to the impact of persistent viral infection on the function of CD4+ T cells and the importance of CD4+ T cells in chronic viral infection." (PMID 30828337, 2019). "While Let-7 upregulation has been observed in hepatocellular carcinoma in association with disease severity, a cancer attributed to viral infection and inflammation, Let-7 upregulation has been associated with protective anti-viral (HIV) cellular CD4+ T-cell responses." (PMID 31134013, 2019). "As B-1 cells are more resistant to apoptosis induced by A/WSN/1933 virus infection than B-2 cells, B-1 cells may be involved in the CD4+ T cell-independent antibody response at early stage and CD4+ T cell-dependent antibody responses may occur later." (PMID 31191534, 2019). "Collectively, our results indicate that CX3CR1+CD11c+ DCs play an important role in generating rapid and effective NK cell activation and Ag-specific CD4+ T-cell responses after viral inoculation at peripheral sites, thereby inducing resistance to viral diseases." (PMID 31316515, 2019). "However, we should take caution because the depletion of CD4+ T cells decreases humoral immune responses to inexperienced virus infection, such as seasonal influenza infection and so on." (PMID 31340866, 2019).